CDK6 (cyclin dependent kinase 6)
Diseases named in the same sentence as CDK6 in open-access papers (continued):
Sharing a sentence is not in itself a finding about the gene and the disease.
cancer (continued). "As previously quoted, palpociclib induces autophagy in cancer, targeting CDK4 and CDK6, via the LKB1 and Ser325 phosphorylation resulting in a CCND1-mediated, reduced activation of AMPK." (PMID 34445095, 2021). "Copy number amplification events in CCND1, CCND3, CDK6, ERBB2, FGFR1, MET, and PIK3CA also showed higher expression compared to wild types across various cancer types." (PMID 34429404, 2021). "Some cancer-related factors including Akt, p-Akt, CCND1, CDK6, and PIK3CA were detected by the western blot." (PMID 33996561, 2021). "The expression of CDK6 can be downregulated as a result of NET-1 protein depression, which provides a therapeutic potential for targeting CDK6 in the treatment of cancer." (PMID 34041269, 2021). "In this study, we show that the CDK4/6 inhibitor abemaciclib inhibits PIM kinase and S6 phosphorylation in cancer cells and concurrent inhibition of PIM, CDK4, and CDK6 suppresses both S6 and Rb phosphorylation." (PMID 32391118, 2020). "Besides inducing the transcription of the tumor suppressor p16INK4A as an endogenous feed-back loop, CDK6 also mediates the transcription of vascular endothelial growth factor A (VEGF-A), a well-characterized angiogenic factor and tumor promoter, thereby linking two hallmark cancer features." (PMID 32260549, 2020). "The spectrum of CDK6-specific PROTACs was extended to von Hippel Lindau (VHL) and cellular inhibitor of apoptosis protein 1 (cIAP1) that are essential for most cancer cells and therefore less likely to be inactivated." (PMID 33133483, 2020). "We demonstrated that overexpression of CDK6 in miR-29b-3p-transfected MDA-MB-231 and Hs578t cells attenuated the inhibitory effect of miR-29b-3p on multiple cancer-related functions, including cell growth, cell G1/S transition, and cell migration." (PMID 32934206, 2020). "Cell division protein kinase 6 (CDK6), a member of the CDK family, which play critical roles in cell cycle progression, apoptosis, cancer invasion, metastasis, and chemoresistance." (PMID 30733646, 2019). "Surprisingly, only eight identified genes (CCND1, CDK6, CDKN2A, KDM5A, MDM2, MLL3, PPP2R1A, and RB1) are shared by UniCovEx and CovEx, and they are all NCG cancer genes." (PMID 30828525, 2019). "As reported for cancer cells and demonstrated by our data, this small-molecule inhibitor exhibits strong selectivity for CDK4 and CDK6 with potent anti-proliferative effects." (PMID 31101827, 2019). "Correlations between LYL1 amplification and increased expression levels of cancer-related genes (MYC, CDK6, PRKACA, and ERBB2) are also observed." (PMID 29716549, 2018). "The studies on the relevance of cell cycle in cancer point out deregulation of p21 and CDKs (CDK4 and CDK6)." (PMID 29426343, 2018). "Additional peaks involving important cancer genes such as SOX2, MYC, VEGFA and CDK6 were also found." (PMID 29370817, 2018). "To investigate how WTAP regulated the cell proliferation of RCC cancer cells, we used western blot to investigate the expression change of cell cycle related protein CDK2, CDK4 and CDK6 by the knockdown or overexpression of WTAP." (PMID 29482572, 2018). "Target genes of miR-22 so far reported include HDAC4, CDK6, SIRT1, SP1, HIF-1α and PTEN, which are involved in cancer progression." (PMID 30379969, 2018). "Specifically, MYC, CDK6, PRKACA, and ERBB2, all well-known oncogenes and cancer markers, were overexpressed in conjunction with LYL1 gene amplification." (PMID 29716549, 2018). "MYC, CDK6, PRKACA, and ERBB2 genes were found to frequently interact with other cancer-related genes." (PMID 29716549, 2018). "Reports have indicated that let-7 inhibits cancer cell proliferation by repressing multiple genes, including RAS, CDK6 and CDC25A." (PMID 28099144, 2017). "We also show that clinically relevant INK mutants can be selected in cancer cells that inactivate CDK4 and CDK6 through different mechanisms and, as a result, also show differing abilities to displace Cdc37 bound to CDK4 or CDK6." (PMID 29091774, 2017).
cancer (continued). "Using Western blot, we found that cell-cycle associated factors were upregulated in the group A antigen-expressing 231-A6 cancer cells, including Cyclin D, Cyclin E, CDK2, CDK6, E2F, and ATM." (PMID 28122343, 2017). "For example, miR‐148a, miR‐34b/c, and miR‐9 downregulate oncogenes, including c‐MYC, E2F3, CDK6, and TGIF2 and are often reduced in cancers." (PMID 28179359, 2017). "FOSL1, BCL2, CDK6, IL7R, RUNX2 and CDC25B have been shown to be targets of JQ1 for transcriptional silencing in other types of cancers." (PMID 27764802, 2016). "Of the top 207 transcripts annotated as ‘cell cycle’ by GO analysis, we focused on nine well-known cell cycle regulators (CCNA2, CCND1, CDK6, CHK1, CHK2, MAPK1, MAP2K1,SKP2, and TFDP1) for further analyses, due to their known functions in cancers." (PMID 26958940, 2016). "Since miR-34a suppresses many oncogenes and cancer stem cell markers including CD44, CDK4, CDK6, c-Met, Notch-1, Notch-2, SIRT1 and DLL1 as its target genes, miR-34a plays important roles in cancer stem cells." (PMID 26580663, 2015). "The new identified targets for cancer therapy in future using luteolin can be CDK2, CDK6, HGFR, MAPK14, FGF." (PMID 26385094, 2015). "The critical well-known function of P21 is to block cell proliferation in normal and cancer cells by inhibiting the activity of kinases important for G1/S transition such as CyclinD/CDK4, CyclinD/CDK6 and CyclinE/CDK2." (PMID 26384350, 2015). "Previous studies showed that miR-34a targets the oncogenes CDK4, CDK6, CCND1, MET, and BCL2, whereas miR-497 targets the oncogenes CCND2 and BCL2 in various types of cancer." (PMID 25909221, 2015). "Among the predicted mRNA targets of miR-22 are known cancer-related genes such as phosphatase and tensin homolog (PTEN), metadherin (MTDH), cyclin-dependent kinase 6 (CDK6), and laminin γ1 (LAMC1)." (PMID 24748979, 2014). "To date, only limited targets including miR-155, IRF5, Blimp1, CCNB1, BCL6, CDK6, Myc, and several others have been identified as IRF4 targets in cancers." (PMID 25207815, 2014). "We discovered novel gene rearrangements in diverse human cancer types, including fusions of ROS1, SLC1A2, RAF1, EWSR1, CDK6, and CLTC." (PMID 23637631, 2013). "In a number of cancer cell lines, miR-16 has been shown to be involved in the induction of apoptosis by targeting BCL-2 and in cell cycle regulation by targeting CDK6, CDC27, and CARD10." (PMID 21698265, 2011). "The aberrant activity of CDK6, NOTCH2, and FGFR2 is described and often associated with more aggressive disease phenotypes in certain types of cancer, but it has not yet been studied in SLCT." (PMID 39592485, 2025). "Common activities shared by CDK4 and CDK6 in cancer have been mostly identified and confirmed evaluating the roles of CDK4 and CDK6 specific inhibitors and, among them the principal is indubitably to promote cell proliferation by directly phosphorylating RB and indirectly through mTORC1 activation." (PMID 39800748, 2025). "In contrast to their known hyperactivity in BC development and progression, p-cMYC and CDK6 levels decreased in the LTT group of benign samples but not in cancer samples." (PMID 40729351, 2025). "Consistent with the effects on the cancer cell growth and survival, knockdown REV-ERBα strongly decreased expression of proteins important for growth, proliferation, and survival including MYC, CDK4, CDK6, CCND2/D3, and BCL2." (PMID 39383000, 2024).
cancer (continued). "CDK6 is a homologue of CDK2, highly similar sequences and structural topology with CDK2 that regulates cell cycle progression, which plays an important role in the progression of various types of cancer." (PMID 36342274, 2023). "Together, the H19/miR-107/CDK6 axis could be exploited as a new target for both diagnosis and treatment of HCC and other cancers." (PMID 37744274, 2023). "CDK6 takes part in the process of cancer development by using the kinase-dependent or non-kinase-dependent function." (PMID 36342274, 2023). "Additionally, the Western blot analysis revealed that the knockdown of SNHG3 significantly reduced the protein levels of proteins involved in the cell cycle (CDK6, CDK4, and Cyclin D1) as well as cancer metastasis (N-Cadherin, Vimentin, and MMP9)." (PMID 37348024, 2023). "It has been shown that FTO exhibits oncogenic effects in BCa by regulating the expression of cell cycle protein-dependent kinase (CDK6), which is closely related to the cell cycle, and mechanistically promotes cancer cell proliferation and invasion in BCa through the FTO/miR-576/CDK6 pathway." (PMID 38117350, 2023). "It regulates cell cycle entry forming, together with CDK6 and one of the three D-type cyclins (D1, D2, and D3), the G1-S transition promoter complex that phosphorylates critical substrates, such as RB1, and promotes excessive cell proliferation in cancer." (PMID 36769158, 2023). "Regarding cellular functions, CDK6 knockdown also significantly inhibited cell viability, colony formation ability, and cell invasion and elicited G0/1-phase arrest of cell cycle, whereas IGF2BP2 overexpression aggravated cancer cell aggressiveness." (PMID 37816718, 2023). "Combining our findings that cdk6-deficient cancer cells lost ABCB1-mediated MDR via co-downregulating PI3K 110α/β, we deem that cdk6 could be a promising target for reversing ABCB1-mediated MDR and inhibiting cancer cell proliferation simultaneously." (PMID 35459184, 2022). "Actually, independent of kinase activity, CDK6 also demonstrate transcriptional regulation activity in malignant tumor." (PMID 35463324, 2022). "CDK6 participates in the process of cancer progression through the kinase-dependent or non-kinase-dependent function." (PMID 35241106, 2022). "A genome-scale CRISPR/Cas9 screen of 342 cancer cell lines revealed that AML cells are highly dependent on cyclin-dependent kinase 6 (CDK6) but not on its close homologue cyclin-dependent kinase 4 (CDK4)." (PMID 35326705, 2022). "CDK6 is overexpressed in cancer cells but only detected at low levels in non-cancer cells and CDK6-null mice have been found to develop normally, suggesting a potential low-toxicity therapeutic strategy through the inhibition of the expression of CDK6." (PMID 35480115, 2022). "It was found that LncRNAs can also control cancer cell metabolism, viz., lncRNA YIYA regulates CDK6 (cell division protein kinase 6) dependent phosphorylation of PFKFB3 (fructose bis-phosphatase PFK2), and thus can convert glucose 6-phosphate (G6P) to fructose-2,6-phosphate." (PMID 36685962, 2022). "Currently, whether CDK4 and/or CDK6 have direct regulatory effects on ABCB1 and ABCB1-mediated MDR in cancer, their roles, and mechanisms are unknown." (PMID 35459184, 2022). "EIF4A1 has been reported to directly determine the selective translation of oncoproteins, such as myc, myb, notch, cdk6, bcl-2 and ROCK1, which are critical regulators contributing to cancer survival, proliferation, migration, invasion, metastasis and chemoresistance." (PMID 36101357, 2022).
cancer (continued). "Using the Cancer Biomarkers database, the authors found >50% of EAC cases to be potentially sensitive to CDK4/CDK6 inhibitors, based on gene alterations in the related pathways, which could be validated by the first in vitro experiments." (PMID 34503107, 2021). "We analyzed CAF correlations with expression profiles of STAT3/CDK2/4/6 and found that out of the 40 TCGA cancer types analyzed via the TIMER server, CAF and STAT3 expressions were correlated in cohorts of 36 cancers types, while CAF and CDK6 expressions were correlated in 34 cancer types." (PMID 33668805, 2021). "Since BCL-2 and MCL-1 proteins may have overlapping anti-apoptotic functions with BCL-XL in cancer cells, we compared the impact of their mRNA expression levels, either alone or in combination with CDK1, CDK6 and WEE1, on the overall survival of TNBC patients." (PMID 34646365, 2021). "Interestingly, positively correlated loci represented cancer driver genes (MYC, PRKCD, RB1, CDK6), molecules involved in immune response (MALT1, PIK3CG), as well as cellular and hormonal signaling (HGF, PTPN13, IGF1, SMAD1, ESR1, CTGF)." (PMID 34368147, 2021). "In order to explore the molecular mechanism via which CDC37L1 inhibited GC cell proliferation and migration, we detected the expression of several cancer signaling pathway factors, such as CDK4, CDK6, Cyclin D1, FAK, PI3K-P110 and mTOR through western blot assays." (PMID 33976724, 2021). "This study therefore discusses the cell cycle’s molecular mechanisms as well as the dysregulation in cancer, CDK structures, and drug complexes, as along with selected CDK inhibitors, including FDA-approved and currently undergoing clinical trial CDK4/CDK6 inhibitors." (PMID 34361615, 2021). "This development starts from non-selective CDK inhibitors to selective CDK4/CDK6 inhibitors, and these have been applied in clinical cancer treatment." (PMID 34361615, 2021). "Meanwhile, our findings also suggested that cancer cells might share similar regulatory mechanisms with PTEN, YY1, and CDK6 controlled by miR-34a." (PMID 33796457, 2021). "Among cancer‐critical genes (defined in the COSMIC Cancer Gene Census), recurrent high‐level amplifications were found only of ERBB2 in two patients, while EGFR and the cell cycle genes CDK6, CCND2, and CCND3 were amplified in one patient each." (PMID 33325154, 2021). "We here discuss the interference of CDK6 and MAPK cascades in cancer and focus on currently available inhibitors in preclinical and clinical contexts, which may open therapeutic options for combined targeted therapy." (PMID 33255177, 2020). "We further screened for CDK6 expression by analyzing the Gene Expression Profiling Interactive Analysis (GEPIA) database and found that the aberrant expression of CDK6 was observed in AML patients among 33 types of human cancer." (PMID 33597968, 2020). "CDK6 and IGF1R are important regulators of cancer progression." (PMID 33219221, 2020). "Targeting kinase-dependent and kinase-independent effects of CDK6 may be thus beneficial for MPN patients and patients suffering from other cancer types." (PMID 33255177, 2020). "We showed a reduction in key cancer related proteins: BCL2, CDK6, p65 and JNK1 kinase, suggesting that reduction of the expression of these proteins might contribute to the effects of BORA depletion on cell survival." (PMID 32268485, 2020). "CDK7 is considered as an attractive target for treating human cancer, as it controls the activity of key enzymes involved in cell cycle progression, including other cyclin-dependent kinases such as CDK1, CDK2, CDK4, and CDK6." (PMID 31076643, 2019). "In addition, other cancer-drivers/oncogenes, e.g. IGF1, CDK6 and PDK1 that are widely involved in oncogenesis, were also suppressed by TSPX in a CAD-dependent manner." (PMID 30863497, 2019).
cancer (continued). "Furthermore, we further investigated the mechanisms that TRIM59 positively regulates CDK6 expression by activation of ERK pathway, which contribute to cancer cell growth and invasion." (PMID 30515965, 2019). "In summary, our data underscore that an increasing repertoire of nonredundant CDK6 functions contribute to cancer cell survival in a context-specific manner." (PMID 30544932, 2018). "While many cell cycle genes are indeed suitable cancer drug targets (e.g. CDK4 and CDK6), other genes may be up-regulated during normal cell division but dispensable for this process." (PMID 29417930, 2018). "However, recent evidence supporting the preferential dependence of cancer cells on interphase CDKs, including CDK4 and CDK6, suggests higher efficiency of a new class of agents targeting CDKs." (PMID 29568361, 2018). "Although CDK4 and CDK6 can potentially bind the same D type cyclins to regulate G1‐S phase progression, it is well established that each CDK and each D cyclin plays unique roles, both in normal development and during cancer progression." (PMID 28778953, 2017). "As we all known, CDK4 plays a key role in mammalian development and cancer, but CDK4-null mutant mice are viable and cell proliferation is not significantly affected in vitro due to compensatory roles played by other CDKs(mainly CDK6)." (PMID 26036633, 2015). "Of the four CDKs (CDK1, CDK2, CDK4 and CDK6), CDK4 and CDK6 are not required for the cell cycle of normal cells but are essential for driving the cell cycle progression in various types of cancer." (PMID 24765199, 2014). "The expression levels of RCC2 and PPIC were actually upregulated in carcinoma tissues relative to normal tissues, whereas CDK6 was not." (PMID 23442884, 2013). "Emerging non-canonical roles of CDK4 and CDK6 could be leveraged to counteract drug resistance in cancer treatment, improving patient outcomes." (PMID 39800748, 2025). "The therapeutic target genes, such as CDK6, HDAC2 and PIGF, exhibited enhanced expression levels in the EMT meta program, confirming that drugs targeting these genes may have significant therapeutic responses in such cancer cell subpopulations." (PMID 38944814, 2024). "Apart from molecular targets expressed in cancer cells of the three types of programs, CD52, CDK6, HDAC2, and PIGF were specifically expressed in inflammatory or EMT meta programs, indicating that drugs against these targets may respond in specific cancer cell subpopulations." (PMID 38944814, 2024). "In these cells, abemaciclib decreased CDK6 phosphorylation and downregulated both p-Rb and Rb levels, in accordance with data from literature showing that CDK4/6 inhibitors reduce Rb phosphorylation and concomitantly decrease the expression of total Rb protein in multiple cancer models." (PMID 35936714, 2022). "Therefore, CDK6 may be potential and secure targets for reversing ABCB1-mediated MDR, since its overexpression has been shown to stimulate cancer cell proliferation." (PMID 35459184, 2022). "These facts indicate that the combined treatment of a CDK6 degrader together with inhibitors of CDK2 and CDK4 may hold promising results and should be considered for future investigations, specifically for INK4low cancer cells." (PMID 35326705, 2022). "In summary, CDK6 does not function solely as a regulator of S-phase entry but can affect cancer cells, in particular different types of leukemic cells, in a way that might be exploited therapeutically." (PMID 34573335, 2021). "CDK6 and TUBB therefore act as network “bridging nodes”, that is, nodes that connect otherwise separate regions of the network and represent proteins through which previously identified candidate cancer genes driving MB development may exert common effects." (PMID 34154646, 2021).